CDK4 (cyclin dependent kinase 4)
Diseases named in the same sentence as CDK4 in open-access papers (continued):
Sharing a sentence is not in itself a finding about the gene and the disease.
alopecia (7 papers, 2019 to 2025). Hair loss usually from the scalp. "Regarding the hair loss item, palbociclib combined with letrozole has been linked to alopecia, and meta-analyses have shown that the combination of a CDK4/6 inhibitor with an AI increases risk of hair loss." (PMID 40107156, 2025). "With CDK4/6 inhibitor-based endocrine therapy, the toxicity profile is much more favorable than that of chemotherapy, with a lower risk of febrile neutropenia, mucositis, alopecia, and other serious complications." (PMID 41479780, 2025). "Indeed, it has been already reported that the risk of alopecia increases in patients receiving combined CDK4/6i and ET treatment compared with those treated with ET alone." (PMID 37509319, 2023). "However, the suitability of targeting CDK4/6 to protect against chemotherapy damage in the hair follicle and prevent chemotherapy‐induced alopecia in patients (i.e. via topical administration) remains to be fully elucidated in vivo." (PMID 31512803, 2019). "Additionally, the CDK4/6 inhibitor itself already presents alopecia as a side effect 69-71." (PMID 35517405, 2022). "Thus, the possibility of using the CDK4/6 inhibitor to prevent paclitaxel-induced alopecia may require fine calibration of drug dosage and drug administration sequence and schedule." (PMID 35517405, 2022). "Alopecia was reported in 25/79 patients, regardless of the CDK4/6i (15 patients on ribociclib, 9 on palbociclib, and 1 on abemaciclib)." (PMID 37509319, 2023). "This underscores that transient, short‐term intrafollicular G1 arrest by topical application of CDK4/6 inhibitors, rather than prolonged G1 arrest by systemic agents, is the most promising strategy to obtain the desired anti‐chemotherapy‐induced alopecia effect." (PMID 31512803, 2019).
atherosclerosis (7 papers, 2016 to 2024). A disease characterized by the build-up of fatty material and calcium deposition in the arterial wall resulting in partial or complete occlusion of the arterial lumen. "Treatment with drugs resulting in CDK4 inhibition via p16INK4a mimetic drugs are currently considered to delay atherosclerosis." (PMID 32971832, 2020). "SARS-CoV-2 interactome strongly connects with the complete ACE2 network through INS, CDK4 (Cyclin-Dependent Kinase 4), CCL2, and ALB (Albumin), all of them associated with atherosclerosis processes." (PMID 33233425, 2020). "Our results showed that ginsenoside Rb1 significantly inhibited the proliferation of vascular cells by inhibiting the interaction of CCDN1 and CDK4, which will provide useful insights for developing novel anti-atherosclerosis drugs by inhibiting cell proliferation." (PMID 38546402, 2024). "Premature atherosclerosis in T2D associates with altered immune cell homeostasis (i.e., T-cell subtype-associated proinflammatory state), diminished p16INK4a and ANRIL expression, and increased CDK4 levels." (PMID 32971832, 2020). "In this study, we demonstrated that Kiom-18, a novel composition of C. cassia, P. densiflora, C. longa and G. glabra, prevents atherosclerosis through the anti-proliferative effect on VSMCs via the regulation of cell cycle-related proteins such as CDK2, CDK4, cyclin D1, cyclin E1, Rb, and PCNA." (PMID 27465365, 2016).
bone tumors (7 papers, 2013 to 2025). "The purpose of discussing this case is to evaluate the activity of cyclin-dependent kinase 4 (CDK-4) and murine double minute 2 (MDM2) expression as a molecular morphology marker of bone tumor formation versus other common immunohistochemistry (IHC) reactions." (PMID 40926903, 2025). "Similar to our observation, the gain of the 12q amplicon was previously found in individual ASPS cases, and the putatively amplified oncogenes on chromosome 12q (e.g., CDK4 and MDM2) were frequently seen in patients with soft tissue and bone tumors." (PMID 35628499, 2022).
COVID-19 (7 papers, 2021 to 2023). A disease caused by infection with severe acute respiratory syndrome coronavirus 2. "Patients receiving CDK4/6 inhibitors had a significantly higher incidence of COVID-19 outbreaks during a prolonged period of longitudinal observation after booster vaccine dosing." (PMID 38023235, 2023). "Furthermore, expression levels of genes controlling cell proliferation and apoptosis, such as TGFB1, CDK4, TNFSF10, and TNFRSF10A, were also found to be dysregulated in CD4+ T cells of patients who recovered from COVID-19." (PMID 34784300, 2021).
Hypertension (7 papers, 2021 to 2025). The presence of chronic increased pressure in the systemic arterial system. "A retrospective study using the OneFlorida Data Trust also found that incident hypertension was the most common cardiovascular adverse event associated with the use of CDK4/6 inhibitors." (PMID 39199640, 2024). "This study demonstrates that the use of CDK4/6 inhibitors is associated with cardiovascular adverse events, such as heart failure and hypertension." (PMID 39199640, 2024). "We summarized the incidence of major adverse cardiovascular events(MACE) and hypertension associated with the use of CDK4/6 inhibitor in randomizedcontrol trials (RCTs) and compared the risks of MACE and hypertension throughnetwork-meta analysis (NMA)." (PMID 39076428, 2023). "Furthermore, this study conducted anetwork meta-analysis (NMA) to compare the MACE and hypertension risks associatedwith the use of CDK4/6 inhibitors." (PMID 39076428, 2023). "Based on the number of reports, cardiac failure and hypertension were commonly reported across the three CDK4/6 inhibitors." (PMID 39199640, 2024). "Among the analyzed cardiovascular toxicities, hypertension was the most frequently reported adverse event with CDK4/6 inhibitors as the primary suspect." (PMID 39199640, 2024). "League table of pair-wised comparisons among endocrine therapyand different CDK4/6 inhibitors in hypertension outcomes using Mantel-Haenszelmethod (with odds ratios and 95% credible intervals)." (PMID 39076428, 2023). "League table of pair-wised comparisons among endocrine therapyand different CDK4/6 inhibitors in hypertension outcomes using the Bayesianframework (with odds ratios and 95% credible intervals)." (PMID 39076428, 2023). "Noteworthy, different CDK4/6i treatment strategies may influence the median onset time of CDK4/6i-related myocardial infarction, hypertension, and ATE (p < 0.05)." (PMID 40520154, 2025). "Additionally, high reporting frequencies of hypertension and cardiac failure were observed, indicating the need for careful monitoring when using CDK4/6 inhibitors." (PMID 39199640, 2024). "Although heart failure was identified as the second most common cardiac adverse event after hypertension in a recent retrospective study, it has not been frequently reported as an adverse event associated with CDK4/6 inhibitors." (PMID 39199640, 2024). "The use of both CDK4/6 inhibitors andhormonal treatment could lead to endothelial injury and hypertension throughvascular inflammation." (PMID 39076428, 2023). "This case report aims to encourage physicians whom patients are treated with cyclin-dependent kinase 4/6 inhibitors to cautiously monitor symptoms suggesting PRES in contexts known to promote its occurrence such as that of arterial hypertension, immunosuppression, and/or autoimmune disease." (PMID 34447643, 2021). "Thus, blocking CDK4/6 and cell cycle progression is protective in gradually progressive models of CKD (e.g., hypertension) but not after an acute ischemic event when rapid cell cycle progression is critical for repair." (PMID 35730565, 2022).
kidney cancer (7 papers, 2020 to 2025). Primary or metastatic malignant neoplasm involving the kidney. "Why RB1 loss does not occur in other cancers (e.g., kidney cancer) is less clear, however, since there is co-occurrence with deregulation of CDK4/6 activity the selective pressure may be limited." (PMID 32242058, 2020). "Targeting CDK4 and CDK6, either separately or in combination with already approved treatments, may improve therapeutic outcomes in patients with kidney cancer." (PMID 39058879, 2024). "Moreover, CDK4, EGFR, and MAP2K2 exhibited moderately high expression levels in cancer cells, with drugs targeting such therapeutic molecules presenting encouraging results in cancer therapy, but their clinical applications in kidney cancer are rarely reported." (PMID 38944814, 2024).
myxofibrosarcoma (7 papers, 2017 to 2025). A malignant fibroblastic neoplasm arising from the soft tissue. "A recent unique case report described clinical improvement in a patient with myxofibrosarcoma harboring a RAF1 S259P mutation and CDKN2A/Bloss who was treated with a combination of the MEK inhibitor trametinib and the CDK4/6 inhibitor palbociclib." (PMID 41200607, 2025). "A case report of a patient with advanced chemotherapy-refractory myxofibrosarcoma harboring RAF1 S259P mutation and CDKN2A/B loss showed complete radiological response on treatment with MEK inhibitor Trametinib and CDK4/6 inhibitor Palbocilib." (PMID 40556788, 2025).
pancreatic adenocarcinoma (7 papers, 2021 to 2023). "In preclinical studies involving pancreatic adenocarcinoma cell cultures with a CDKN2A gene mutation, CDK4/6 inhibitors demonstrated antiproliferative activity against these cancer cells." (PMID 38137564, 2023). "Trametinib in combination with hydroxychloroquine (HCQ) or CDK4/6 inhibitors for pancreatic adenocarcinoma showed promising efficacy in preclinical studies." (PMID 37817078, 2023). "Silibinin caused G1 arrest by decreasing the expression of Cyclin D1, Cyclin E2 and CDK4 and inducing increased expression of p21 and p15 in the human pancreatic adenocarcinoma cell line SW1990." (PMID 35401195, 2022). "Importantly, the combination of MEK and CDK4/6 inhibitors in pancreatic adenocarcinoma induce senescence including the release of SASP factors enriched in pro-angiogenic proteins promoting tumour vascularisation and enhancing drug delivery and efficacy." (PMID 35184131, 2022). "Indeed, the combination of CDK4/6 and MEK inhibitors has shown remarkable promise in pre-clinical and clinical studies of Ras-driven cancers, such as non-small cell lung cancer (NSCLC) and pancreatic adenocarcinomas." (PMID 33456709, 2021).
soft tissue tumors (7 papers, 2016 to 2025). "For instance, ring chromosomes containing amplified copies of MDM2, often accompanied by CDK4, are also present in subtypes of soft tissue tumours." (PMID 39322633, 2024). "After that, we performed IHC expressions of p16 and CDK4 markers on the unstained slides of these soft tissue tumors." (PMID 37016649, 2023). "In the present study, we have examined the IHC expression of p16 and CDK4 in soft tissue tumors." (PMID 37016649, 2023). "CDK4 expression was seen more in malignant adipocytic tumors as compared to benign adipocytic tumors and other non-adipocytic soft tissue tumors." (PMID 37016649, 2023). "The correlation of p16 and CDK4 expression with overall survival in various soft tissue tumors could not be studied because of an inadequate follow-up period." (PMID 37016649, 2023).
adrenocortical carcinoma (6 papers, 2017 to 2025). "Taken together, these data underline the impact of CDK4 and CDK6 inhibitors in treating adrenocortical carcinomas." (PMID 29283884, 2017).
brain cancer (6 papers, 2013 to 2024). A primary or metastatic malignant neoplasm affecting the brain. "One example is a CDKN2A deletion that sensitizes brain cancer cells to palbociclib (a CDK4/6 inhibitor) and to knockouts in CDK4 and CDK6 genes." (PMID 35614096, 2022). "Here, we test various combinations of highly selective and potent CDK4/6 inhibitors with commonly used cytotoxic drugs in several cancer cell lines derived from lung, breast and brain cancers, for their cell-killing effects as compared to monotherapy." (PMID 31600301, 2019). "GLR2007 was also shown to inhibit the enzymatic activity of CDK4 and CDK6, and induce G1 arrest in cell line U87-MG, a model of GBM brain cancer." (PMID 36033522, 2022).
gallbladder cancer (6 papers, 2015 to 2025). "Neferine inhibits the proliferation of human gallbladder cancer cells through the CDK4/CDK6/CyclinD1 pathway." (PMID 40138292, 2025). "Kaempferol has been shown to hinder cell growth and induce apoptosis in human gallbladder cancer cells via Cyclin D1/CDK4 signaling pathway." (PMID 39161904, 2024). "The transition from the G0 to G1 phase of the cell cycle is regulated in part by a mitosis-promoting factor, which consists of cyclin D1 and CDK4 in gallbladder cancer cells." (PMID 29899865, 2018).
Hepatic steatosis (6 papers, 2020 to 2022). Steatosis is a term used to denote lipid accumulation within hepatocytes. "Previous reports suggested that high levels of CDK4 can cause hepatic steatosis, fibrosis, and hepatocellular carcinoma in non-alcoholic fatty liver mouse models and patients with fatty liver." (PMID 35193513, 2022). "They demonstrated that inhibition of Cdk4 can reverse hepatic steatosis in NAFLD mice, providing evidence that aberrant Cdk4 signaling can promote dysregulation of lipid metabolism in certain contexts." (PMID 32226926, 2020). "Targeting CDK4 in aged mice by a specific CDK4 inhibitor eliminates hepatic steatosis." (PMID 33334026, 2020). "CDK2 and CDK4 are considered potential targets for prevention and treatment of hepatic steatosis." (PMID 33334026, 2020). "Indeed, knockdown of p300 or inhibition of CDK4 in old mice inhibits hepatic steatosis." (PMID 32936538, 2020). "Other studies suggested that inhibition of CDK4 plays an important role in hepatic fatty acid metabolism in reducing CCAAT-enhancer-binding proteins (C/EBPα)/ histone acetyltransferase p300 complexes and eliminating hepatic steatosis." (PMID 33334026, 2020).
Infertility (6 papers, 2007 to 2024). "A Cdk2 and Cdk6 dKO also results in infertility in both sexes, while a Cdk4 and Cdk6 dKO displays the same infertility seen in a Cdk4 single KO, with total female infertility and partial male infertility, signifying that Cdk6 does not have a dominant phenotype in mouse fertility." (PMID 32731332, 2020). "The knockdown of CDK4, another member of CDKs, induced infertile in mice." (PMID 28831078, 2017). "Although Cdk6−/− mice show no overt defects in gametogenesis, Cdk4 deletion results in female infertility from birth and early‐onset infertility in male mice." (PMID 31566717, 2019). "CDK4 and -6 are the preferred catalytic subunits of cyclin D. Mice lacking the CDK4 gene display a dwarfism-like phenotype, infertility, and hypocellularity in many organs." (PMID 17295909, 2007).
myocardial infarction (6 papers, 2021 to 2025). Gross necrosis of the myocardium, as a result of interruption of the blood supply to the area, as in coronary thrombosis. "The most commonly reported cardiac adverse events following CDK4/6 inhibitor administration were myocardial infarction (n = 266, 12.9%), followed by cardiac disorder (n = 250, 12.1%) and atrial fibrillation (n = 234, 11.3%)." (PMID 39199640, 2024). "Consistent disproportionality emerged for all the CDK4/6 inhibitors on PE, with significantly increased reporting of DVT with abemaciclib (17; 1.98, 1.22–3.19), cerebrovascular accidents with palbociclib (248; 1.22; 1.07–1.38), and myocardial infarction with ribociclib (41; 1.82; 1.33–2.48)." (PMID 33917020, 2021).
ovarian tumors (6 papers, 2012 to 2025). "In summary, our findings indicate that Kirenol influences the PI3K/AKT/CDK4 signaling pathway to exert its anti-cancer properties in ovarian tumors." (PMID 38415456, 2025). "At the transcriptomic level, we observed a significantly higher expression of CDK4 in the ovarian tumour tissues compared to the normal tissues." (PMID 38612869, 2024). "CDKN2A (p16INK4a), which is known to inhibit CDK4 and CDK6, was deleted or downregulated in 21% of the ovarian tumours." (PMID 38612869, 2024).
acute kidney injury (5 papers, 2022 to 2026). Sudden and sustained deterioration of the kidney function characterized by decreased glomerular filtration rate, increased serum creatinine or oliguria. "Here, we present a case of suspected nephrotoxicity associated with abemaciclib (CDK4/6 inhibitor), which turned out to be a pseudo-acute kidney injury due to its interference with the tubular secretion of creatinine." (PMID 38915820, 2024). "This is intresting as transient inhibtion of CDK4 has been shown to protect renal epithelial cells from DNA damage and apoptosis during acute kidney injury." (PMID 40457431, 2025). "Unlike the reparative role of cell cycle progression following acute kidney injury, these data suggest that blocking cell cycle progression by inhibiting CDK4/6, but not cyclin D1, protects against chronic kidney injury." (PMID 35730565, 2022).
Arthritis (5 papers, 2019 to 2023). Inflammation of a joint. "Bone pain (5–28.7% vs. 2.2–17.2%), back pain (2–13.4% vs. 8–11.2%), and arthritis (3.6–33.6% vs. 0.32%) were reported less frequently in patients receiving the combination of CDK4/6 inhibitors with ET." (PMID 37293258, 2023). "Only one trial has reported the incidence of arthritis induced by CDK4/6 inhibitors in the adjuvant setting." (PMID 37293258, 2023). "Inhibition of CDK4/6 prevented joint destruction in animal models of arthritis by inhibiting synovial cell proliferation and perhaps by exerting chondroprotective effects in the arthritic joints." (PMID 34849618, 2022). "Collectively, there is evidence that CDK4/6 inhibitors possess a protective role in treatment-related arthritis." (PMID 34198899, 2021). "Considering that arthritis and arthralgia are based on a complex inflammatory process, CDK4/6 inhibitors may attenuate E2F2 activity in synovium and cartilage and reverse, at least in part, the inflammation caused by aromatase inhibitors." (PMID 33530456, 2021). "Moreover, the CDK4/6 inhibitor palbociclib suppressed arthritis in RA animal models." (PMID 30828336, 2019). "In the present study, we observed chondroprotective effects in an animal model of arthritis and selective suppression of MMP-1/MMP-3 in RASFs using a CDK4/6 inhibitor." (PMID 34849618, 2022). "CDK4/6 selective inhibitor (CDKI), palbociclib suppressed the severity of arthritis." (PMID 34849618, 2022). "Because the inhibition of CDK4/6 reduced the excess MMPs induced by cytokines from synovial fibroblasts, the combination use of CDKI with anti-inflammatory agents such as biologic agents might be an ideal therapeutic strategy as we have previously shown in an animal model of arthritis." (PMID 34849618, 2022).
B-cell lymphomas (5 papers, 2021 to 2026). "The data provide a rational basis for integrating CD79B-directed ADCs with mTOR or CDK4/6 inhibitors to prevent or overcome treatment resistance of aggressive B cell lymphomas." (PMID 41668618, 2026). "Noteworthy findings included the high activity of CDK6 substrates in the Pfeiffer cell line, a diffuse large B-cell lymphoma line, aligning with reports that CDK4/6 inhibitors are effective against aggressive B-cell lymphomas." (PMID 41035678, 2025). "Similarly, CDK4 overexpression aligns with increased proliferative capacity, and its role in lymphomagenesis is supported by studies demonstrating the sensitivity of CDK4/6-driven malignancies to pharmacologic inhibition and poor prognosis in DLBCL and other B-cell lymphomas." (PMID 41472741, 2025).